MET (MET proto-oncogene, receptor tyrosine kinase)
Diseases named in the same sentence as MET in open-access papers (continued):
Sharing a sentence is not in itself a finding about the gene and the disease.
tumor (continued). "Papillary tumors, which are classified as type I or type II based on tumor histology, account for 10% of RCC tumors, and while familial cases are linked to c-MET mutations the cause of sporadic cases remains unclear." (PMID 30863721, 2019). "Additionally, the increase in ctDNA EGFR copy number is consistent with the growth of MET inhibitor resistant tumor cells." (PMID 30849971, 2019). "Gene expression levels measured relative to the adjacent normal cortex sample revealed numerous oncogenic driver genes with >2-fold higher expression in the tumour and clone samples, including genes encoding AURKA/B, CDK4/6, FGFR1, AKT1/2, MTOR, MET, PIK3C2A, WNT5A, SFRP4, and MYC." (PMID 30736342, 2019). "The selective MET inhibitor KRC-00715 suppressed tumor growth in a Hs746T mouse xenograft model." (PMID 31557260, 2019). "In this study we asked whether MET is involved in the regulation of immune checkpoint pathways and immune cell function and then validated our findings by analyzing tumor tissues from patients and a public tumor database." (PMID 31480591, 2019). "However the aberrant expression of c-MET and of HGF is implicated in neoplastic cells spreading and tumor progression in many solid tumors." (PMID 30642077, 2019). "Moreover, tumor cell lines were insensitive to capmatinib in vitro and in vivo, excluding any tumor cell-intrinsic c-MET dependency in this study." (PMID 31616408, 2019). "We showed that BsAb-5 could inhibit HGF-mediated CSC-like phenotypes and tumor development, serving as an inhibitory c-MET antibody." (PMID 29187584, 2019). "The rationale for choosing these cell lines was their origin as well as their differential expression pattern of HH signaling components: The MET-1 cell line originated from a primary tumor that gave rise to a metastatic lesion from which the cell line MET-4 was generated." (PMID 31867038, 2019). "However, the influence of MET overexpression by the tumor on the efficacy of PD-1/PD-L1 blockade is unclear." (PMID 31480591, 2019). "It was hypothesized that tumor heterogeneity, HER2, or MET subclones initiated an independent pathway for tumor progression." (PMID 29713646, 2018). "As such, in HGF-autocrine tumors, MET inhibitors target both tumor cells and endothelial cells." (PMID 30208970, 2018). "This may methodically mask potential regulatory effects of miR-31 on c-MET in certain sub-populations of tumor cells." (PMID 29463215, 2018). "Furthermore, the IHC assay revealed that sensitive HCC cells showed higher levels of total MET and P-MET expression, which was defined as greater than 50% of cells with strong membrane staining (IHC 3+) in tumor xenografts." (PMID 29712569, 2018). "However, in certain murine tumor types, inhibition of MET has been reported to diminish infiltration of antitumor neutrophils, resulting in increased tumor growth and metastasis." (PMID 30349530, 2018). "In a mouse xenograft model, it was shown that overexpression of miR-31, as well as supplementary therapy with a MET inhibitor could overcome chemoresistance, decrease a size of the tumor and improve overall survival of taxane-treated mice." (PMID 29707144, 2018). "We hypothesized that hypoxia induced by VEGF antibody treatment might activate MET signaling which led to the increased potential of tumor invasion and metastasis." (PMID 29712569, 2018). "Indeed, heparin promotes tumor-cell motility and invasion through activation of c-MET signaling pathway." (PMID 30352967, 2018). "As a consequence, blockade of the MET pathway results in inhibition of tumor growth." (PMID 30544501, 2018). "Higher levels of MET showed promoted cell proliferation, invasion and tumor budding in CRC." (PMID 29581707, 2018). "CD44 also interacts with c-MET and improves tumor cell migration, invasion and metastasis." (PMID 30352967, 2018). "Indeed, in human GC tissues positive for H. pylori, we also observed that activated MET was highly expressed in tumour‐infiltrating macrophages." (PMID 30160350, 2018).
tumor (continued). "Similarly, a phase II study showed that the dual MET/VEGFR2 inhibitor foretinib had anti-tumor activity in patients with papillary renal carcinoma and a high response rate in patients with germlineMET mutations." (PMID 29560266, 2018). "In the past years, many c-MET inhibitors have being discovered and developed to suppress tumor." (PMID 30360560, 2018). "Thus, in this Hs746t preclinical model of MET exon 14 skipping, small molecule kinase inhibitors, including merestinib, showed more compelling anti-tumor effect than most anti-MET antibodies." (PMID 29188469, 2018). "Migration of HT1080 cells along a rhodocetin-αβ gradient was concentration-dependent and could be inhibited by blocking MET, suggesting that rhodocetin-αβ induced tumor cell motility along the NRP1-MET signaling axis, similar as in ECs." (PMID 29854288, 2018). "In this highly heterogeneous tumor, c-MET contributes to OS cells transformation and proliferation." (PMID 29520051, 2018). "Previously, miR-34a has been regarded as a tumor suppressor through targeting MET, a RTK (receptor tyrosine kinase) playing a key role in promoting cell proliferation via transducing extracellular stimuli to intracellular signalling circuits, through PI3K/AKT signaling." (PMID 30463570, 2018). "Finally, the inhibition of the tumor–stroma interaction by MET/HGF interception induces stroma remodeling, which results in increased drug delivery and restoration of the response to gemcitabine." (PMID 30544501, 2018). "We could visualize different tumour areas with high and low expression of the targeted MET transcripts (respectively)." (PMID 29728634, 2018). "In this sense, miR-26a may well alleviate tumor angiogenesis of HCC via blocking HGF/c-MET pathway and it might be a novel therapeutic strategy for HCC patients with aberrant HGF and c-MET." (PMID 30360560, 2018). "Interestingly, at cut-off values >5% of the tumour cells with positive staining, the co-expression of EGFR/HER-2, EGFR/HER-3, EGFR/c-MET, and EGFR/HER-2/HER-3 were all associated with a poorer disease free-survival in the univariate analysis." (PMID 29731973, 2018). "Consequently, the aberrant activation of this HGF/c-MET signaling pathway promotes tumor cell proliferation and angiogenesis, inhibition of apoptosis, and EMT programming and is linked to an overall poor patient prognosis and survival rate." (PMID 29725606, 2018). "Thus, the HGF/c-MET signaling pathway induces different phenotypes and enhances the aggressive nature of tumor cells during cancer progression." (PMID 30352967, 2018). "The observed in vivo anti-tumor effect of merestinib and crizotinib is consistent with the potent in vitro anti-proliferative effect, inhibition of pMET and downstream signaling of the activated MET pathway in Hs746t cells." (PMID 29188469, 2018). "Sequencing was performed on the metastatic tumor sample but no MET mutation was identified and no MET gene amplification was observed." (PMID 30474572, 2018). "Using a xenograft model, we next investigated the role of exosomal MET in tumour growth in vivo." (PMID 30160350, 2018). "However, patients with MET-high tumor tended to show longer survival when treated with an additional MET inhibitor." (PMID 29088885, 2017). "Significant difference in MET overexpression was found in tumor clinical stage and pT status." (PMID 28052014, 2017). "However, the greatest reduction in tumor volume (to 17.9 ± 2.2 % of control mice receiving IgG treatment) was seen in the group of mice that received triple therapy (HGF inhibition + c-MET inhibition + gemcitabine)." (PMID 29100344, 2017). "Furthermore, in an in vivo study, analysis of tumor tissues from patients who developed resistance to cetuximab or panitumumab showed the emergence of MET amplification in more than 40% (3 out of 7) of the cases." (PMID 28002810, 2017).
tumor (continued). "In summary, these results indicate that MMP-2 and TIMP-1 possibly aided by c-MET may promote tumor progression by enhancing angiogenesis and tumor invasion." (PMID 28234925, 2017). "Moreover, co-expression of TGF-β2 and p-c-MET in the same tumor cells was rarely detected (see arrowhead), showing that these two antigens exhibit almost mutually exclusive staining patterns among patients and within the tumor from the same patient." (PMID 29238047, 2017). "Indeed, the only AXL-positive cases with evidence of tumor shrinkage also had positive MET expression." (PMID 29050231, 2017). "Furthermore, combined MET/PI3K inhibition led to enhanced anti-tumor activity in vivo in tumors harboring PIK3CAH1047R." (PMID 28532501, 2017). "The patient died of her disease quickly after tumor resection and 4 cycles of postoperative chemotherapy; therefore, we were unable to test whether the patient could benefit from MET inhibitor therapy." (PMID 28638113, 2017). "However, treatment with the multikinase inhibitor crizotinib led to tumor shrinkage in two of four patients with highly MET-amplified (MET:CEP7 >5) gastroesophageal cancers." (PMID 29108334, 2017). "It has been demonstrated that discontinuation of MET tyrosine kinase inhibitors results in increased and prolonged MET activation, coupled to enhanced tumor growth in vitro and in vivo, suggesting that MET inhibitors will need to be combined with other therapies." (PMID 28968967, 2017). "In addition, in their cohort, a 74-year-old woman with stage IV PSC (widespread disease with lung, liver, and bulky mesenteric disease) was noted 3 months after resection of a tumor that harbored MET exon 14 skipping." (PMID 28638113, 2017). "However, little is known about the role of the different c-MET fragments in tumor progression so far." (PMID 28212658, 2017). "In addition, the SSM samples analyzed showed significant co-localization of MYSM1 with tyrosine kinase c-MET in tumor cell clusters." (PMID 28978033, 2017). "Mutants of MET are known to promote tumorigenesis, tumor progression, and drug resistance." (PMID 28418880, 2017). "Conversely, downregulation of MET expression in tumor cells can lower their tumorigenic potential." (PMID 28485003, 2017). "Oncogenes ALK, ROS1, RET and MET have been characterized as indicators for tumor growth." (PMID 28716024, 2017). "So they can target tumor cells directly and indirectly by binding to c-MET and HGF, respectively." (PMID 28485003, 2017). "Altogether, our results indicate that the NRF2 silencing-mediated miR-206 regulation could suppress BCRP levels through c-MET/EGFR modulation, providing an additional underlying molecular mechanism for the tumor sensitization by NRF2 inhibition." (PMID 29291022, 2017). "As the affinity of the H2 cys-diabody and H2 minibody for c-MET are comparable to that of onartuzumab, this is probably due to the high molecular weight of 89Zr-onartuzumab that results in slower blood clearance and prolonged tumour exposure." (PMID 28315949, 2017). "Ex vivo, tumour c-MET immunohistochemistry was correlated with the imaging results." (PMID 28315949, 2017). "This could be one of the mechanisms mediating the observed reduction in tumor volume observed with c-MET inhibition in our in vivo model." (PMID 29100344, 2017). "MET amplification may also contribute to tumor metastasis as MET expression was significantly higher in metastatic cancers than primary cancers." (PMID 29348894, 2017). "In this respect, we previously reported that the combined inhibition of both SMO and MET exerted a significant anti-proliferative and pro-apoptotic effect in this model in vitro and in vivo, with tumor regressions and complete response in 100% of HCC827-GR tumors xenografted in nude mice." (PMID 28416737, 2017). "In addition to antitumor effects, we provide novel evidence that miR-206 can inhibit tumor resistance by suppressing the c-MET/EGFR-BCRP axis." (PMID 29291022, 2017).
tumor (continued). "Monitoring changes in total MET and tumor HGF levels may have clinical utility for identifying patients most likely to benefit from combination therapy with inhibitors targeting the MAPK pathway and HGF/MET signaling." (PMID 28147313, 2017). "It is possible that there could be other mechanisms besides CBL/MET interactions that could lead to the in vivo tumor growth decrease with sh-CBL." (PMID 28835699, 2017). "The remaining case showed stable MET copy numbers in primary tumor and metastasis." (PMID 27894094, 2017). "Notably, the primary tumor had a clonal high-level amplification of MET (with an average of over 70 copies of MET per cancer cell) that was not present in the post-treatment autopsy sample after treatment with the MET inhibitor." (PMID 29872714, 2017). "However, we included the 111In-OA-NBC paired control molecule in each experimental animal as a valid control to determine specific tumour uptake, as well as ex vivo analysis for c-MET expression and necrosis." (PMID 28315949, 2017). "Our initial insight was that constant drug combination strategies that guarantee progression free response for tumor cell populations with considerable heterogeneity and/or MET activation, required EGFR TKI concentrations that were considerably higher than are typically clinically feasible." (PMID 28287179, 2017). "This implies that the combination of HSP27 silencing and MET kinase inhibition could more steadily control the growth of MET‐addicted tumours and suggests that a similar mechanism drives full cytotoxicity driven by HSP27 silencing and targeted agents." (PMID 28182330, 2017). "Unexpectedly, both cMBP-GGG and cMBP-AOC showed uniform high pancreatic uptake, which may be a result of peptide degradation, as there was very low c-MET expression in the pancreas compared to tumor tissue, as confirmed by RT-PCR." (PMID 28485003, 2017). "On the contrary, two GSC lines (6 and 8) had a higher expression of MET than in tumor samples." (PMID 28960893, 2017). "TAS-115 monotherapy may benefit SS patients whose tumours are dependent upon either c-MET or PDGFRα signalling by functioning as a multiple tyrosine kinase inhibitor to suppress c-MET as well as PDGFRα pathways." (PMID 28511645, 2017). "Therefore, volitinib selectively inhibited tumor growth in a series of human tumor xenograft models with aberrant MET signaling." (PMID 27013592, 2016). "Tumor MET levels have been shown to decrease in both mice and patients treated with tivantinib." (PMID 27579536, 2016). "To identify tumor lines with aberrant c-Met signaling suitable for further examination of the effect of ABT-700, we evaluated a panel of 35 human cancer cell lines for MET amplification, c-Met protein expression and their dependence on c-Met activity for growth in vitro." (PMID 26879245, 2016). "Our initial limited “targeted” analyses of PTEN, KRAS, BRAF, PI3KCA and MET did not elucidate predictors of response to MEK inhibitors with any tumor-specific genetic variants." (PMID 26683364, 2016). "The HGF/MET signaling axis may also be involved in tumor progression, as increased MET and HGF expressions and enhanced activation of pro-HGF are all seen in clear cell RCC." (PMID 27338367, 2016). "In addition, it has been observed that c-MET inhibition augmented Th cell recognition by decreasing the TGF-β production by tumor cells." (PMID 27923392, 2016). "In addition, cotreatment of SMO inhibitor and MET inhibitor to HCC827-GR xenografted tumors further suppressed tumor volume, since constitutive MET activation was observed in HCC827-GR cells." (PMID 28105432, 2016). "Interestingly, phosphorylation of ERK1/2 and AKT downstream effectors were inhibited by restoration of miR-206 in cancer cells, indicating that tumor-suppressive miR-206 inhibited dual signaling networks activated by MET and EGFR." (PMID 26646588, 2016). "MET amplification was defined as a MET/CEP7 ratio ≥2 or cluster signals in >10% of tumor cells." (PMID 27013592, 2016).
tumor (continued). "Pharmacological FAS blockade might result in rapid changes in the lipid composition of the tumor cell membrane, which could impair a correct cellular localization of c-MET." (PMID 27923392, 2016). "Likewise, for patients with TNBC, treated with CMF, MET amplification showed prognostic significance with adjustments made for nodal status and tumours size (HR = 6.1; 95% CI: 1.79-20.9, p=0.004)." (PMID 27175600, 2016). "The differences in phosphorylation between tumor tissue and normal tissue might be explained by a higher and more heterogeneous baseline level of phosphorylation of c-MET in tumor tissue." (PMID 26742633, 2016). "Moreover, in concordance with other studies, high MET and HGF copy number in tumours from cohort 2 were associated with higher cell proliferation (SPF)." (PMID 27175600, 2016). "For example, our findings that concurrent treatment with crizotinib can re-sensitize EGFR-mutant tumours with MET amplification to rociletinib suggest that personalized targeting of multiple resistance mechanisms may be of significant clinical utility." (PMID 27283993, 2016). "This indicates the expansion of MET‐expressing (stem‐like) cells, likely benefitting of a selective advantage under therapeutic pressure and possibly mediating the well‐known radiotherapeutic refractoriness of the recurrent tumor." (PMID 27138567, 2016). "Consistently—even alone—MET inhibition can impair tumor growth in vivo." (PMID 27138567, 2016). "In addition, differences in protease activity or activation of other receptor tyrosine kinases such as MET can have profound influences on tumor cell invasion." (PMID 27738329, 2016). "Among the five miRNAs, miR-329 and miR-206 could both target 3′-UTR of MET and exert tumor suppressor function in NSCLC." (PMID 26909600, 2016). "The MET/CD44 axis seems to be an important component of the CSC response in this HNSCC tumor model." (PMID 26880935, 2016). "The c-MET-specific T helper (Th) cells could also recognize dendritic cells (DCs) pulsed with c-MET expressed tumor cell lysates." (PMID 27923392, 2016). "In addition, inhibition of c-MET with the small molecule c-MET inhibitor (SU11274) showed potent anti-tumor activity in OCCC using in vitro and in vivo experiments." (PMID 27917934, 2016). "Proteomic analysis of AKT, ERK1/2, MEK1/2, EGFR and c-MET phosphorylation was conducted for normal and tumor ischemic tissue samples from all 20 patients, and relative quantification of phosphorylation was calculated by determining the AUC of annotated peaks in relation to each other (% area)." (PMID 26742633, 2016). "Protein expression of MET was not related to genetic polysomy or amplification, but was putatively caused by modifications in micro-environmental and tumor signaling pathways." (PMID 27105539, 2016). "INC280 showed preliminary anti-tumor efficacy as a single agent in 50% of patients with EGFR wild-type NSCLC with MET dysregulation, as confirmed by FISH (MET/centromere ratio ≥2.0 or MET gene copy number ≥5) or IHC (MET H-score ≥150 or 50% of tumor cells with a staining intensity of 2+ or 3+)." (PMID 27013592, 2016). "The preclinical attributes of ABT-700 in blocking c-Met signaling, inducing apoptosis and suppressing tumor growth in cancers with amplified MET provide rationale for examining its potential clinical utility for the treatment of cancers harboring MET amplification." (PMID 26879245, 2016). "In tumor tissue-based analyses, overall MET amplification rate was 1.7% (10/590)." (PMID 27421137, 2016). "In addition, two monoclonal antibodies generated against MET inhibited CRC tumor growth in a mouse xenograft model." (PMID 26243458, 2016). "Finally, in vitro and in vivo, we show that MET inhibition radiosensitizes tumors, by improving the overall control of tumor growth, and, most importantly, by converting the danger of GBM stem‐like cell‐positive selection into the benefit of their depletion." (PMID 27138567, 2016).